NRSN2 (neurensin 2)
Description:
May play a role in maintenance and/or transport of vesicles.
Synonyms: C20orf98; dJ1103G7.6
Tractability: Antibody: its Gene Ontology location is reachable by antibodies, with high confidence; UniProt predicts a signal peptide or a membrane-spanning region. PROTAC: ubiquitination databases record sites on it.
Gene: Protein-coding gene on chromosome 20 (346,705 to 359,660, forward strand). Ensembl gene ENSG00000125841.
Subcellular location: Membrane
Subcellular location (Human Protein Atlas): Vesicles; Cytosol; Nucleoplasm
Gene Ontology:
Molecular function: protein binding
Biological process: nervous system development
Cellular component: plasma membrane; neuron projection; neuronal cell body; transport vesicle; cytoplasmic vesicle; membrane
Genetic constraint (gnomAD): Loss-of-function variants: 17 observed, 16.23 expected, observed/expected ratio (o/e) 1.05, 90% interval 0.72 to 1.57. The upper end of that interval is the gene's LOEUF score, 1.57, which puts it in group 6 of 6, group 1 being the genes least tolerant of losing a copy. Missense variants: 260 observed, 286.65 expected, observed/expected ratio (o/e) 0.91, 90% interval 0.82 to 1. Synonymous variants: 100 observed, 122.91 expected, observed/expected ratio (o/e) 0.81, 90% interval 0.69 to 0.96.
Homologues: Orthologues: chimpanzee NRSN2 (99% identical), macaque NRSN2 (98% identical), dog NRSN2 (92% identical), pig NRSN2 (87% identical), rabbit NRSN2 (81% identical), guinea pig NRSN2 (72% identical), mouse Nrsn2 (57% identical). Paralogues in human: NRSN1 (31% identical).
Diseases named in the same sentence as NRSN2 in open-access papers:
NRSN2 is named in the same sentence as 16 diseases in open-access papers, as found by Europe PMC text mining. Sharing a sentence is not in itself a finding about the gene and the disease. The quoted sentences say what the papers report.
osteosarcoma (9 papers, 2022 to 2024). A usually aggressive malignant bone-forming mesenchymal neoplasm, predominantly affecting adolescents and young adults. "A previous study has revealed that NRSN2 is highly expressed in osteosarcoma tissues and promotes cell proliferation via the dysregulation of PI3K/Akt/mTOR and Wnt/β‐catenin signaling pathways." (PMID 38457049, 2024). "NRSN2 overexpression was confirmed to be related with the malignant phenotype in osteosarcoma, ovarian cancer, and non-small cell lung cancer." (PMID 38457049, 2024). "BMSC-derived EVs promoted the proliferation, invasion, and migration of osteosarcoma cells via the lncRNA MALAT1/miR-143/Neurensin-2 (NRSN2)/Wnt/β-catenin axis." (PMID 37377390, 2023). "Bone marrow-derived mesenchymal stem cell-derived extracellular vesicles (BMSC-EVs) can promote proliferation, invasion, and migration of osteosarcoma cells via the MALAT1/miR-143/NRSN2/Wnt/β-catenin axis." (PMID 36211364, 2022). "It has been found that BMSC-derived EVs (BMSC-EVs) promotes the invasion, proliferation and migration of osteosarcoma cells through lncRNA MALAT1/miR-143/NRSN2/Wnt/β-Catenin axis." (PMID 35860555, 2022). "Bone marrow-derived mesenchymal stem cell-derived extracellular vesicles (BMSC-EVs) can promote the proliferation, invasion, and migration of osteosarcoma cells via the MALAT1/miR-143/NRSN2/Wnt/β-catenin axis." (PMID 36211364, 2022). "BMSC-EVs can transfer MALAT1 into osteosarcoma cells, thus increasing the expression of MALAT1 and NRSN2, reducing the expression of miR-143, and activating Wnt/β-catenin pathway in osteosarcoma cells." (PMID 35860555, 2022). "In particular, Bone Marrow Mesenchymal Stem Cells-Derived Extracellular Vesicles (BMSC-EVs) were found able to promote proliferation, invasion and migration of osteosarcoma cells via the MALAT1/miR-143/NRSN2/Wnt/beta-catenin axis both in vitro and in vivo, as detailed in a next section." (PMID 38835012, 2024). "Similarly, Zhou and Xu showed that BMSC-derived exosomes inhibited osteosarcoma progression by transferring miR-1913 or miR-150 to osteosarcoma cells to suppress NRSN2 or IGF2BP1 expression, respectively." (PMID 37377390, 2023). "In particular, it has been demonstrated that BMSC-EVs-treated osteosarcoma cells showed increased MALAT1 and NRSN2 expressions, and activated Wnt/β-catenin pathway due to MALAT-1 sponging activity versus miR-143." (PMID 38835012, 2024). "Exo-miR-150 targets IGF2BP1, Exo-miR-195 targets KIF4A, Exo-miR-206 targets NRSN2, and RGD-Exo targets Rad18, along with other pathways that impede the evolution of osteosarcoma." (PMID 39605980, 2024).
Anxiety (2 papers, 2021). Intense feelings of nervousness, tension, or panic often arise in response to interpersonal stresses. "Strikingly, defeated Neurensin-2 KO mice showed less social avoidance, anhedonia, or anxiety-like behavior following the stress, relative to WT controls." (PMID 33742167, 2021). "On the contrary, in a companion paper, we reported notable depressive- and anxiety-like behaviors following the upregulation of Neurensin-2 in DG CCK cells, and here we confirmed that these mice retain normal behavioral response to the SSRI." (PMID 33723417, 2021). "Overexpression of Neurensin-2 in DG CCK cells led to depression-like and anxiety-like behaviors, a similar phenotype to that observed in the SMARCA3 cKO mice." (PMID 33742167, 2021). "In addition to anhedonic and despair-like behaviors, Neurensin-2 overexpression resulted in anxiety-like behavior in the open field test, without a deficit in locomotion." (PMID 33742167, 2021).
developmental delay (2 papers, 2016 to 2019). "This deletion included SOX12 and NRSN2, both of which have been identified as pivotal genes associated with developmental delays." (PMID 31087544, 2019). "Interestingly, we found that most of the affected patients with developmental delays were caused by the defects of multiple genes which were usually associated with TBC1D20, SOX12, and NRSN2 genes." (PMID 31087544, 2019). "This microdeletion involved SOX12 (OMIM#601947) and NRSN2 (OMIM#610666), which were previously reported to induce developmental delays in patients with 20p13 microdeletions." (PMID 31087544, 2019).
hepatocellular carcinoma (2 papers, 2014 to 2024). A malignant tumor that arises from hepatocytes. "Notably, decreased expression of NRSN2 was reported to be associated with hepatocellular carcinoma." (PMID 24956270, 2014). "By contrast, it was demonstrated that NRSN2 is downregulated in hepatocellular carcinoma tissues and exerts a suppressive role during tumorigenesis." (PMID 38457049, 2024). "On the contrary, downregulation of NRSN2 was reported to serve as a suppressive gene in hepatocellular carcinoma." (PMID 38457049, 2024).
ovarian carcinoma (2 papers, 2024). A malignant neoplasm originating from the surface ovarian epithelium. "NRSN2 is also closely associated with the malignant phenotype of ovarian cancer." (PMID 38457049, 2024).
breast carcinoma (1 paper, 2023). "Neurensin‐2 (NRSN2) also promotes breast cancer metastasis by activating the PI3K/AKT/mTOR and NF‐κB signaling pathways, and melittin suppresses EGF‐induced cell motility and invasion by inhibiting the PI3K/Akt/mTOR signaling pathway in breast cancer cells." (PMID 37249285, 2023).
depression (1 paper, 2021). "We also observed an impairment in nesting behavior of Neurensin-2 overexpressing mice, an indication of compromised well-being, which is known to be induced by stress models of depression." (PMID 33742167, 2021). "In contrast, 73% of the Neurensin-2 overexpressing mice showed SI ratio below 1, an indication of vulnerability to depression." (PMID 33742167, 2021).
laryngeal carcinoma (1 paper, 2024). Carcinoma that arises from the laryngeal epithelium. "However, the function of NRSN2 in HPV-infected laryngeal carcinoma (LC) remains unclear." (PMID 38569536, 2024).
cancer (4 papers, 2020 to 2024). A tumor composed of atypical neoplastic, often pleomorphic cells that invade other tissues. "Multiple studies have revealed the important roles of NRSN2 in the development of various types of cancers." (PMID 38457049, 2024). "Several studies in cancer models suggest that Neurensin-2 regulates the PI3K/AKT/mTOR pathway in an unknown mechanism." (PMID 33723417, 2021). "Several of these HSEPs have been reported in other contexts to play key roles in tumour progression by cancer cell proliferation (NRSN2, WISP2, SPRX1, LCK), metastasis (GOLM1, STC1, MGAT5B), and stemness (STC1, TMEM59), as well as promoting angiogenesis (ANGPTL4) and host immunosuppression (CD70)." (PMID 33050615, 2020). "Neurensin 2 (NRSN2), a small neuronal membrane protein that localized in small vesicles of neural cells, is found to be dysregulated in multiple types of human cancers." (PMID 38457049, 2024).
tumor (4 papers, 2020 to 2024). "The results revealed that hypoxia stimulated cells to synthesize EVs proteins involved in enhancing tumour cell proliferation (NRSN2, WISP2, SPRX1, LCK), metastasis (GOLM1, STC1, MGAT5B), stemness (STC1, TMEM59), angiogenesis (ANGPTL4), and suppressing host immunity (CD70)." (PMID 33050615, 2020). "In our study, NRSN2 was verified to be regulated by LUESCC, and was highly expressed in ESCC tumor samples." (PMID 38457049, 2024).
NRSN2 also shares sentences with these, for which no sentence is quoted: esophageal squamous cell carcinoma (2 papers); autism (1); epilepsy (1); non-small cell lung carcinoma (1); prostate hyperplasia (1); schizophrenia (1).